APP (amyloid beta precursor protein)
Diseases named in the same sentence as APP in open-access papers (continued):
Sharing a sentence is not in itself a finding about the gene and the disease.
colitis (4 papers, 2023 to 2025). Inflammation of the colon. "The marked histological differences indicate that male AppNL-G-F mice are more prone to severe colitis and subsequent neoplastic transformation, possibly due to a more aggressive inflammatory milieu driven by APP mutations." (PMID 41279101, 2025). "To investigate the causal role of microbial communities in AD progression, we performed fecal microbiota transplantation (FMT) in APP/PS1 transgenic mice using donor microbiota from healthy wild-type mice or dextran sulfate sodium (DSS)-induced colitis mice." (PMID 40486731, 2025). "In this study, fecal microbiota transplantation (FMT) from healthy donors or those with colitis significantly modulated cognitive behavior, Aβ pathology, and inflammatory cytokine profiles in APP/PS1 transgenic mice." (PMID 40486731, 2025). "Further, APP processing or the levels of BACE1 and beta‐amyloid degrading enzymes were altered by acute colitis." (PMID 40457749, 2025). "We showed that microglial phagocytosis was not responsible for the reduced beta‐amyloid deposition nor was APP processing significantly altered following acute colitis." (PMID 40457749, 2025).
Crohn disease (4 papers, 2020 to 2022). A gastrointestinal disorder characterized by chronic inflammation involving all layers of the intestinal wall, noncaseating granulomas affecting the intestinal wall and regional lymph nodes, and transmural fibrosis. "Thus, neurons and microglia from persons with more surface GRP78 are likely to have an enhanced capability to take up extracellular materials such as Tau and APP which, in contrast to the beneficial effect this has in Crohn’s Disease, in AD is deleterious." (PMID 36227739, 2022). "Using the DGIdb database, four key NLRP3 inflammasome-related genes (APP, HSP90AB1, NFKB and TLR4) were further selected as potential druggable targets for Crohn’s disease treatment." (PMID 36685554, 2022).
hematoma (4 papers, 2016 to 2025). A hematoma is a collection of blood from a vascular structure into an extravascular space. "Immunohistochemical staining indicated that APP accumulated in the region affected by hematoma at 24 and 72 h after ICH induction." (PMID 35773404, 2022). "Our results align with prior research indicating elevated levels of APP, S100β, and NFL proteins in regions affected by hematomas." (PMID 39981435, 2025). "In earlier ICH studies, we observed transient accumulation of amyloid precursor protein (APP) and SC1/hevin within axons in the peri-hematoma at 1 and 3 days." (PMID 26743212, 2016).
Hydrocephalus (4 papers, 2015 to 2021). Hydrocephalus is an active distension of the ventricular system of the brain resulting from inadequate passage of CSF from its point of production within the cerebral ventricles to its point of absorption into the systemic circulation. "The finding of early elevations, but later normalization, of APP and other CSF biomarkers is in agreement with the notion of acute and chronic stages of hydrocephalus advanced by McAllister and others." (PMID 28212403, 2017). "Experimental studies have shown that axoplasmic transport is impaired in hydrocephalus, synaptogenesis is modulated by APP, and APP serves as a neurodevelopmental trophic factor." (PMID 28212403, 2017). "Further, differential regulation of APP processing and amyloid isoforms may provide insight into specific pathways involved in the pathogenesis of hydrocephalus and its neurological sequelae and/or the repair mechanisms at play in neurological recovery." (PMID 28212403, 2017). "Amyloid precursor protein is known to be released by axonal injury or stretch; thus it is plausible that ventricular distention in hydrocephalus, and axonal stretch as a consequence, could represent the origin of the observed changes in CSF APP." (PMID 25738507, 2015).
Hypoglycemia (4 papers, 2017 to 2023). A decreased concentration of glucose in the blood. "Reduced O-GlcNAcylation of APP and Tau due to hypoglycemia is found to be associated with their pathological features in AD brain." (PMID 31143098, 2019). "Thus, alteration of synaptic function in other brain areas like the arousal system, or even non-neuronal and metabolic effects, such as hypoglycaemia previously shown for APP/APLP2-DKO mice, might be a potential cause of neonatal death." (PMID 28690498, 2017).
hypothyroidism (4 papers, 2018 to 2024). Abnormally low levels of thyroid hormone. "Rat models of hypothyroidism exhibited increases of APP protein, tau hyperphosphorylation, proinflammatory cytokines and spatial memory impairments, indicating that hypothyroidism represents an important risk factor of developing sporadic forms of AD." (PMID 30618632, 2018). "In conclusion, the current study revealed that Melissa officinalis extract ameliorates the induced hypothyroidism as well as the associated brain damage by enhancing the cellular redox balance, alleviating the neurotoxicity through abrogating the misfolded protein aggregates precursors (APP & MAPT)." (PMID 37368180, 2023). "These suggest a possible link between hypothyroidism, increased APP synthesis, and processing, as well as decreased NGF maturation and function." (PMID 32259096, 2018). "Therefore, the mRNA expression of the amyloid precursor protein (APP) and microtubules-associated protein tau (MAPT) was examined in the brain tissues to evaluate the damaging effect associated with hypothyroidism." (PMID 37368180, 2023). "Thus, hypothyroidism leads to an overproduction of APP, which is now available to be processed by the increased activity of β-secretase." (PMID 32259096, 2018).
Impaired glucose tolerance (4 papers, 2016 to 2023). An abnormal resistance to glucose, i.e., a reduction in the ability to maintain glucose levels in the blood stream within normal limits following oral or intravenous administration of glucose. "In striking contrast, significantly reduced levels of fasting blood glucose in APP/PS1 mice appeared after Akk treatment, and impaired glucose tolerance was improved, but only the high-fat diet group showed statistical differences (p < 0.05, respectively)." (PMID 32321934, 2020). "Male APP/PSEN1, Sorcs1 -/-, and Sorcs1 -/- x APP/PSEN1 mice continued to display impaired glucose tolerance compared to WT mice." (PMID 26916443, 2016).
lymphoma (4 papers, 2015 to 2025). A malignant (clonal) proliferation of B- lymphocytes or T- lymphocytes which involves the lymph nodes, bone marrow and/or extranodal sites. "Furthermore, APP‐Fe NC nanocomplexes, which contain anti‐PD‐L1 peptides (APP), trigger Fenton's reaction and ultimately cause a disturbance in cellular redox balance in lymphoma cells." (PMID 40936204, 2025).
myocardial infarction (4 papers, 2014 to 2022). Gross necrosis of the myocardium, as a result of interruption of the blood supply to the area, as in coronary thrombosis. "However, as in the case of troponin determination in the acute phase of myocardial infarction, it may be clinically relevant to prove an increase or decrease in APP concentration as an indicator of CNS ischemia." (PMID 35268287, 2022).
neuritis (4 papers, 2021 to 2025). A neuropathy arising from inflammation of one or more nerves. "Several studies have shown that a high AA diet in AD mouse models helps to prevent cognitive dysfunction caused by abnormal processing of amyloid precursor protein (APP), thereby reducing the formation of insoluble Aβ in neuritis plaques." (PMID 40362847, 2025). "Nixon’s group noted the accumulation of subcellular aggregates and AVs in dystrophic neuritis and further studies have supported the accumulation of these AVs associated with dying neuritis in APP/PS1 mice." (PMID 34782612, 2021). "The kinesin-dependent APP axonal transport is affected by HAP1 in neurons, and lack of HAP1 decreases the transport of APP vesicles from the cell body to neuritis." (PMID 36824265, 2023).
pheochromocytoma (4 papers, 2015 to 2021). "In this experiment, we hypothesized that mutated APP gene (APP-sw) might be helpful in making pheochromocytoma cells less viable and more susceptible to cell death triggering mechanisms." (PMID 25821818, 2015). "Additionally, pheochromocytoma cells are immune to death receptor ligands so alternate use of TNF-α and TRAIL was justified with regard to cell viability, APP processing, and molecular markers of autophagy." (PMID 25821818, 2015).
psoriasis (4 papers, 2009 to 2024). An autoimmune condition characterized by red, well-delineated plaques with silvery scales that are usually on the extensor surfaces and scalp. "Moreover, the secretory n-terminal domain of APP (sAPP) has been implicated in the regulation of keratinocyte proliferation, the underlying cause of psoriasis." (PMID 37382595, 2023). "The involvement of multiple cell types in psoriasis, particularly in the more frequent APP pathway, was further confirmed at the protein level." (PMID 38289616, 2024). "APP is upregulated and re-distributed in psoriasis lesions strikingly similar to Wnt5a and APP stimulates both proliferation and mobility of keratinocytes." (PMID 19399181, 2009). "However, our study suggests an avenue for enhancing psoriasis treatment by inhibiting intercellular signaling pathways conducive to inflammation, such as APP." (PMID 38289616, 2024). "Communication between hair follicles and mast cells, melanocytes, and myeloid cells only occurred in psoriasis, focusing on COL4A2/CD44 and APP/CD74 ligand-receptor pairs." (PMID 38289616, 2024). "In psoriasis, Langerhans cells were predominantly and strongly involved via COLLAGEN and LAMININ pathways, while a variety of cell types participated in the APP pathway, primarily featuring T-cells in the MIF pathway." (PMID 38289616, 2024). "We identified APP pathway-related ligand receptor proteins, including APP and CD74 (CD74 Antigen), with upregulated protein expression in pathological tissue sections of psoriatic skin (Psoriasis/Normal skin Ratio in CD74 protein: 1.202; Psoriasis/Normal skin Ratio in MIF protein: 1.239)." (PMID 38289616, 2024). "Therefore, the induction of APP by Wnt5a/IFN may contribute to increased keratinocyte turnover and migration in psoriasis." (PMID 19399181, 2009).
Spastic paraparesis (4 papers, 2018 to 2024). Partial loss of the ability to move the lower limbs accompanied by spasticity of the lower limbs. "AD variants with mutations such as APP can also have various motor manifestations such as hyperactive reflexes, extremity weakness, and spastic paraparesis." (PMID 29497704, 2018). "The pathophysiology of spastic paraparesis in PSEN1‐associated fAD is not well understood and may relate to altered processing of γ‐secretase substrates other than APP." (PMID 38824433, 2024). "In this particular case, spastic paraparesis was the initial feature, which we speculate might explain the lesser phenotypic changes (e.g., protein aggregation) in HSs from the PS1 compared with APP variants." (PMID 32589876, 2020).
trisomy 21 (4 papers, 2013 to 2021). A chromosomal disorder consisting of the presence of an extra chromosome 21. "Genetic mutations in the genes coding for presenilin 1 (PS1), presenilin 2 (PS2), amyloid beta precursor protein (APP), and Trisomy 21 may also be involved in the pathogenesis of AD." (PMID 33265993, 2020). "The discrepancy may be related to our study population being all trisomy 21, including APP." (PMID 24462566, 2014).
adenoma (3 papers, 2022 to 2025). A neoplasm arising from the epithelium. "In the present study, however, APP expression was downregulated by high expression of miRNA-660-5p and miRNA-664a-5p, suggesting that the associations of miRNA-660-5p and miRNA-664a-5p with APP may promote tumor progression from adenoma to carcinoma." (PMID 35875068, 2022). "Therefore, Arid and Ap16 samples included hyperplasia/adenoma, while Apik and APP samples contained intramucosal carcinoma." (PMID 40761291, 2025). "To determine whether APP and its cleavage products are altered in PHPT, we performed immunohistochemistry (IHC) and parathyroid-specific proteomic profiling assays comparing the expression of key molecules in β-amyloidogenesis in PHPT adenomas versus normal parathyroid glands." (PMID 40492090, 2025).
aneurysm (3 papers, 2016 to 2022). Bulging or ballooning in an area of an artery secondary to arterial wall weakening. "Among them, six hub genes might be the core genes for the rupture of aneurysms, including APP, JUN, GSK3B,ErbB2, PPBP and THBS1." (PMID 35432454, 2022). "Others have observed microangiopathies and aneurysms throughout the microvessels of the liver, kidneys and the brain of APP/PS1 mice, suggesting a causal relationship between amyloidogenesis and systemic vascular dysfunction, at least in the APP/PS1 mouse." (PMID 31708792, 2019).
apraxia (3 papers, 2021 to 2025). Apraxia is a neurological disorder characterized by the inability to perform tasks or movements, despite having the desire and physical ability to perform them. "For instance, patients with APP mutations are more likely to have apraxia/agnosia and perform worse than LOAD." (PMID 36313020, 2022).
Autoimmunity (3 papers, 2019 to 2024). The occurrence of an immune reaction against the organism's own cells or tissues. ",90,91,92In vivo LXR knock-out exacerbates autoimmunity in WT mice and amyloid-β pathology in APP/PS1 mice, while agonism ameliorates pathology in experimental autoimmune encephalitis and intracerebral haemorrhage." (PMID 38550989, 2024). "Compared with APP+/+ mESC-TEP-transplanted mice, the percentage of IFNγ-producing CD4 T cells in APP−/− mESC-TEP-transplanted mice showed a larger increase, which is probably due to enhanced anti-Aβ autoimmunity in APP−/− mESC-TEP-transplanted AD mice." (PMID 32849642, 2020).
cardiac hypertrophy (3 papers, 2021 to 2023). "CD74_MIF, CD74_APP and CD74_COPA pairs were significantly enriched by B cells and macrophages at different stages of cardiac hypertrophy, indicating that CD74 played a crucial role in inflammation activity in cardiac hypertrophy." (PMID 36805782, 2023). "The neuroinflammation signaling pathway and HMGB1 signaling pathway were not among the top ten canonical pathways and none of the top 5 canonical pathways from the core analysis of the 8-molecule dataset overlapped with the top 5 canonical pathways from the cardiac hypertrophy with APP dataset." (PMID 33946401, 2021).
familial disease (3 papers, 2015 to 2025). "By looking at the causes of FAD, genetic analyses have indicated that mutations in APP (amyloid precursor protein), PSEN-1 (presenilin 1) or PSEN-2 (presenilin 2) genes are the cause of the different types of familial disease." (PMID 25954151, 2015). "The APP/PS1 mouse model is an over-expression model of APP mutations typically found in early onset, familial disease, which accounts for <1% of AD cases and does not replicate all aspects of the human disease or human amyloid-plaques." (PMID 29623063, 2018).
fibrosis (3 papers, 2024 to 2025). the formation of excess fibrous connective tissue in an organ or tissue in a reparative or reactive process. "Prominent pancreatic fibrosis was also observed in APP/PS1 mice fed with low VA diet." (PMID 40341393, 2025).
head and neck cancer (3 papers, 2019 to 2025). A primary or metastatic malignant neoplasm affecting the head and neck. "Co-expression analyses indicated that SPP1 was co-expressed with MMP9, ARPC1B, and APP in head-neck cancer." (PMID 31849319, 2019). "The results showed that SPP1 was over-expressed in patients with head-neck cancer, and the top 3 genes co-expressing with SPP1 were Matrix Metallopeptidase 9 (MMP9), Actin Related Protein 2/3 Complex Subunit 1B (ARPC1B) and Amyloid Beta Precursor Protein (APP)." (PMID 31849319, 2019).
head and neck squamous cell carcinoma (3 papers, 2019 to 2026). A squamous cell carcinoma that arises from any of the following anatomic sites: lip and oral cavity, nasal cavity, paranasal sinuses, pharynx, larynx, and salivary glands. "For example, a 7-mRNA signature (AATF, APP, GNPDA1, HPRT1, LASP1, P4HA1 and ILF3) of head and neck squamous cell carcinoma (HNSCC) shows a moderate predictive ability for 5-year OS (AUC for training set, 0.75; testing set, 0.66)." (PMID 31396442, 2019).
heart failure (3 papers, 2009 to 2016). Inability of the heart to pump blood at an adequate rate to meet tissue metabolic requirements. "While in the cortex of female mice, CHF elicited higher expression of APP; in the hippocampus, heart failure significantly increased the expression of BACE1 and CTFs." (PMID 23737953, 2013). "However, the lack of overt change in myocardial histology and β1-adrenergic receptor expression suggest the absence of any advanced heart failure and adrenergic desensitization in APP/PS1 hearts." (PMID 19551139, 2009).
Infertility (3 papers, 2020 to 2022). "Two of the proteins stably interacting specifically with A189V FSHR, amyloid precursor protein (APP) and TGF-beta receptor type-1 (TGFBR1), have been indicated to have a role in gonadal development or linked to infertility." (PMID 35471239, 2022). "Other key proteins such as ANXA2 and APP were overexpressed in secondary infertility group compared with control group (p < 0.05)." (PMID 32372034, 2020). "Moreover, the validation of proteomic results using WB suggests that APP can serve as a seminal plasma marker in diagnosis of secondary infertility." (PMID 32372034, 2020). "Validation of key proteins suggests that ANXA2 can be a screening biomarker for both primary and secondary infertility, whereas CDC42 and SEMG2 can be useful candidate biomarkers for primary infertility and APP for secondary infertility." (PMID 32372034, 2020). "Western blot validation showed overexpression of ANXA2 and CDC42, and underexpression of SEMG2 proteins in primary infertility; and overexpression of ANXA2 and APP proteins in secondary infertility." (PMID 32372034, 2020).
iron deficiency (3 papers, 2014 to 2019). "We propose, therefore, that under physiological conditions, miR-346 activity on the APP 5′-UTR depends upon iron deficiency." (PMID 30470799, 2019). "In the case of APP, IRP1 binds to an IRE motif in the 5′ UTR of APP mRNA to inhibit translation and thus inhibit iron export in iron deficiency." (PMID 30150923, 2018).
meningitis (3 papers, 2020 to 2022). A disorder characterized by acute inflammation of the meninges of the brain and/or spinal cord. "The CSF levels of amyloid-β (Aβ) peptide, an APP cleaved product, are found at lower levels in adult with tuberculous meningitis, supporting its association with meningitis." (PMID 35634471, 2022). "Kumar and his colleagues demonstrated that APP knockout mice had a reduced survival, while mice transgenic for APP had an improved survival in a model of infectious meningitis." (PMID 33013850, 2020). "In contrast to APP/PS1 double-transgenic mice, the blood-brain barrier is severely impaired in meningitis allowing Ac2-26 to exert beneficial effects in the brain." (PMID 32331524, 2020).
oral squamous cell carcinoma (3 papers, 2013 to 2023). "Also, CD74-MIF/COPA/APP interactions were expressed in TME of oral squamous cell carcinoma after chemotherapy." (PMID 35784460, 2022). "TFAP2A binds to the promoters of tectonic family member 1 (TCTN1) and amyloid precursor protein (APP)to induce malignancy (proliferative, migratory and invasive capacity) in the oral squamous cell carcinoma (OSCC)." (PMID 37291585, 2023). "In cancer patients, increased APP gene expression was more common in tumor tissue of oral squamous cell carcinoma patients than in non-cancerous matched tissue samples." (PMID 23368879, 2013).